MYH9 (myosin heavy chain 9)
Diseases named in the same sentence as MYH9 in open-access papers (continued):
Sharing a sentence is not in itself a finding about the gene and the disease.
type 2 diabetes (5 papers, 2012 to 2025). "Recently, MYH9 rs3752462 was associated with cerebrovascular blood flow (CBF) in patients with type 2 diabetes." (PMID 29862302, 2018). "Our results suggest that subjects with MYH9 risk alleles have an amplified risk of CKD in the presence of type 2 diabetes, thus underscoring the importance to aggressively monitor subjects with type 2 diabetes for renal diseases." (PMID 23285077, 2012). "In this study we show that SNPs in the MYH9 gene are associated with renal phenotypes in a mixed ancestry population of South Africa with type 2 diabetes." (PMID 23285077, 2012).
autism (4 papers, 2011 to 2025). Persistent deficits in social interaction and communication and interaction as well as a markedly restricted repertoire of activity and interest as well as repetitive patterns of behavior. "Correlation analysis in clinical settings also suggests that MYH9 is a susceptibility gene linked to autism, schizophrenia, and intellectual disabilities, indicating that MYH9-RD patients may benefit from preventive monitoring for neurological diseases." (PMID 39404399, 2024). "This consistent change in expression patterns supports the hypothesis that Arrb2 contributes to autism pathogenesis by regulating Myh9, Dnmt1, and Brd4, although differently in different tissues." (PMID 40428426, 2025). "A recent study of de novo mutations found in multiple neurodevelopmental disorders revealed that MYH9 is one of only three affected genes shared by autism, schizophrenia and intellectual disability, and de novo mutations for MYH10 are reported for both schizophrenia and autism." (PMID 26542704, 2015).
colon cancer (4 papers, 2020 to 2024). "Further functional analyses confirmed that the knockdown of MYH9 decreased the primary activity of colon cancer cells." (PMID 39149512, 2024). "A previous study demonstrated that MYH9 promotes colon cancer progression by modulating FA assembly." (PMID 38504374, 2024). "Notably, validation using an independent cohort of colon cancer patients established that co-expression of MYH9 and other genes correlated with poorer clinical outcomes in terms of overall and disease-free survival (p < 0.001)." (PMID 39149512, 2024). "MYH9 is responsible for the formation of FAs, thereby promoting colon cancer progression." (PMID 38504374, 2024).
Congenital thrombocytopenia (4 papers, 2012 to 2025). Thrombocytopenia with congenital onset. "MYH9-related disease (MYH9-RD) is a rare autosomal dominant genetic syndrome characterized by congenital thrombocytopenia associated with the risk of developing progressive nephropathy, sensorineural deafness, and presenile cataract." (PMID 22558294, 2012). "MYH9-related disease (MYH9-RD) is an autosomal dominant disorder characterized by congenital thrombocytopenia with giant platelets associated with the risk of developing progressive nephropathy during infancy or adult life, sensorineural deafness and presenile cataract." (PMID 22558294, 2012). "MYH9-related disorders are characterized by large platelets and congenital thrombocytopenia." (PMID 36553283, 2022). "In all the cases, diagnosis of MYH9-RD based on the findings of congenital thrombocytopenia, giant platelets, and identification of pathognomonic NMMHC-IIA leukocyte inclusions by immunofluorescence assay, and was confirmed by identification of the causative MYH9 mutation." (PMID 24980457, 2014).
head and neck squamous cell carcinoma (4 papers, 2022 to 2024). A squamous cell carcinoma that arises from any of the following anatomic sites: lip and oral cavity, nasal cavity, paranasal sinuses, pharynx, larynx, and salivary glands. "Studies have shown that in head and neck squamous cell carcinoma, low expression of MYH9 leads to poor prognosis, thus supporting the role of MYH9 as a human tumor suppressor." (PMID 36374212, 2022). "Furthermore, SLC7A11, IFN2, and MYH9 were significantly upregulated in kidney clear cell carcinoma (KIRC) and head and neck squamous cell carcinoma (HNSC)." (PMID 38862242, 2024).
renal cell carcinoma (4 papers, 2022 to 2024). "A separate study demonstrated that MYH9 facilitates the progression of renal cell carcinoma and resistance to sunitinib through AKT signaling." (PMID 39440063, 2024). "MYH9 increases the proliferative and metastatic potential of renal cell carcinoma cells by stimulating AKT signalling pathway." (PMID 37875476, 2023). "Other studies have shown that MYH9 binds to CXCR4 and promotes the migration and invasion of renal cell carcinoma." (PMID 36374212, 2022). "However, to the best of our knowledge, there has been no research about the role of MYH9 in renal cell carcinoma." (PMID 35318312, 2022).
schizophrenia (4 papers, 2011 to 2024). A major psychotic disorder characterized by abnormalities in the perception or expression of reality. "So far, it is still arguable for MYH9 about its susceptibility to schizophrenia, especially in Caucasian population." (PMID 26193471, 2015). "In the first and second stages, the authors found a potential association of MYH9 with schizophrenia (allelic P-value = 0.047)." (PMID 26193471, 2015). "In another study conducted in Taiwanese sample, MYH9 was found as a vulnerable gene for neuropsychological defined subgroups of schizophrenia patients (P-value = 0.0059 with haplotype analysis)." (PMID 26193471, 2015).
Alport syndrome (3 papers, 2018 to 2023). A rare renal disease characterized by glomerular nephropathy with hematuria progressing to end-stage renal disease (ESRD), frequently associated with sensorineural deafness, and occasionally with ocular anomalies. "Due to the overlap of clinical manifestations, MYH9-RD associatedwith renal impairment was considered a variant of Alport syndrome, designated asFechtner syndrome." (PMID 29782633, 2018). "Other diseases such as Alport syndrome and MYH9 mutations were reported as the cause of CKD." (PMID 37332753, 2023).
bleeding disorders (3 papers, 2011 to 2025). "Myosin Heavy Chain 9 (MYH9) encodes non-muscle myosin heavy chain IIA, and its abnormality in the hematopoietic system alters platelet cytoskeletal components, leading to bleeding disorder." (PMID 38956669, 2024).
cervical carcinoma (3 papers, 2024 to 2026). A carcinoma arising from either the exocervical squamous epithelium or the endocervical glandular epithelium. "Targeting the KIF23/MYH9/MCM2/PCNA axis sensitises cervical cancer cells to cisplatin." (PMID 41940421, 2026).
COVID-19 (3 papers, 2020 to 2024). A disease caused by infection with severe acute respiratory syndrome coronavirus 2. "Our current data shows that myosin inhibitor could reduce MYH9-mediated SARS-CoV-2 entry into cells, providing a therapeutic target for treating COVID-19." (PMID 34873039, 2021). "In our study, we discovered that MYH9, highly expressed in human lungs, is a host factor for SARS-CoV-2 infection and could be a target for COVID-19 prevention." (PMID 34873039, 2021). "Plasma protease C1 inhibitor was upregulated in COVID-19 patients, displaying a positive correlation, while FIBA, talin 1, filamin A, myosin heavy chain 9 and the beta subunit of hemoglobin, displayed negative correlations." (PMID 33096722, 2020).
cyst (3 papers, 2020 to 2024). A sac-like closed membranous structure that may be empty or contain fluid or amorphous material. "We focused on this timepoint because it precedes the Myh9/10epi-cko invagination defect at E13.5 and the cyst formation at later stages." (PMID 38857279, 2024). "The site of CVI cyst is the forebrain, where the expression of the MYH9 has been shown to have a central role in morphogenesis, and in particular in the cell shape changes." (PMID 33308197, 2020). "Using live imaging, we showed that even before any cyst formation Myh9/10epi-cko mutant incisors already developed a clear cell movement phenotype at E13.0, in which posterior suprabasal cells often reciprocated and displayed reduced efficiency of convergent cell movement." (PMID 38857279, 2024).
Glanzmann thrombasthenia (3 papers, 2011 to 2026). "Additionally, 23 subjects had MYH9 gene variants and one patient was affected by Glanzmann thrombasthenia." (PMID 41731342, 2026).
Hermansky-Pudlak syndrome (3 papers, 2015 to 2024). Hermansky-Pudlak syndrome (HSP) is a multi-system disorder characterized by oculocutaneous albinism, bleeding diathesis and, in some cases, neutropenia, pulmonary fibrosis, or granulomatous colitis. "However, one study included subjects without a conclusive diagnosis of IPFD, another excluded patients with GT, BSS, MYH9-related disorder, and Hermansky-Pudlak Syndrome, and the third investigated only patients with PSDs, limiting their generalizability." (PMID 38292347, 2024).
inherited thrombocytopenia (3 papers, 2021 to 2025). An instance of thrombocytopenia that is inherited. "Reports for the use of TPO-RA in inherited thrombocytopenia, such as MYH9-related disorders or Wiskott–Aldrich syndrome, showed benefit on transfusion needs and hemostasis in a total of 80% of patients." (PMID 34650908, 2021).
ischemic stroke (3 papers, 2020 to 2023). A stroke disorder caused by obstruction of blood flow to the brain, due to thrombotic (local blood clot formation) or embolic (due to a blood clot or other material traveling from another site) event. "Additionally, MYH9 has been identified to participate in BBB dysfunction in ischemic stroke and to mediate oxidative stress-induced neuronal apoptosis." (PMID 32711535, 2020).
leukemia (3 papers, 2017 to 2021). A malignant (clonal) hematologic disorder, involving hematopoietic stem cells and characterized by the presence of primitive or atypical myeloid or lymphoid cells in the bone marrow and the blood. "Taken together, these results indicated over-expressed MYH9 might associate with favorable prognosis in leukemia." (PMID 27437869, 2017).
neuroblastoma (3 papers, 2016 to 2024). Neuroblastoma (NB) is the most common solid, extracranial childhood tumor. "In addition to its predicted targeting of MYH9, miR-124-3p was predicted to target additional cytoskeletal genes (PLEC, ITGB1, VIM, and ACTN4) from our panel, which were overexpressed in the resistant SK-N-ASCis24 neuroblastoma cell model." (PMID 33330445, 2020). "These cytoskeletal genes (MYH9, PLEC, ITGB1) and mesenchymal markers (VIM, ACTN4), were previously reported by our lab to be up-regulated with cisplatin resistance development and involved in phenotypic and morphological modulation observed in our neuroblastoma cell model." (PMID 33330445, 2020). "The cytoskeletal genes MYH9, PLEC, ITGB1, VIM, and ACTN4, were previously reported by our lab to drive EMT-like morphological transformation and increased invasiveness (2.5 fold) in the MES SK-N-ASCis24 neuroblastoma cell line, coinciding with resistance development." (PMID 33330445, 2020).
nodular fasciitis (3 papers, 2024 to 2025). A self-limiting, rapidly growing, non-encapsulated benign neoplasm that arises from the soft tissues. "Recently, RT-PCR and other methods have shown that USP6 gene rearrangement is detected in up to 90% of cases, and MYH9 is identified in approximately 70% of cases, making it useful for the diagnosis of nodular fasciitis." (PMID 39816285, 2024).
orofacial cleft (3 papers, 2016 to 2024). A disorder of facial skeleton that is characterized by cleft lip and/or cleft palate that result in feeding, speech and hearing problems caused by failures during development. "Based on these observations, genetic association between variants in the MYH9 gene and orofacial cleft has been demonstrated in several studies." (PMID 36830605, 2023). "Numerous researchers have investigated the MYH9 gene, particularly the SNP rs7078, in the context of orofacial cleft formation, mostly in Asian and American populations." (PMID 39200165, 2024). "Nonsynonymous variants in MYH9 and ABCA4, which were detected in 6 and 5 individuals, respectively, were identified to be the most frequent risk loci in nonsyndromic orofacial clefts in the Taiwanese population." (PMID 27527345, 2016). "Nonsynonymous variants in MYH9 and ABCA4 were identified to be the most frequent risk loci in nonsyndromic orofacial clefts in the Taiwanese population." (PMID 27527345, 2016).
pulmonary fibrosis (3 papers, 2020 to 2025). Chronic progressive interstitial lung disorder characterized by the replacement of the lung tissue by connective tissue, leading to progressive dyspnea, respiratory failure, or right heart failure. "The persistent upregulation of Myh9 indicates its potential involvement in pulmonary fibrosis associated with pSS, possibly through the dysregulation of thrombopoiesis and platelet function." (PMID 41389878, 2025). "Additionally, TP53TG1 has been identified as interacting with Myh9, leading to the downregulation of its expression, inhibition of fibroblast activation, and mitigation of pulmonary fibrosis." (PMID 41389878, 2025). "TP53TG1 as a novel MYH9 protein inhibitor to suppress fibroblast activation and pulmonary fibrosis." (PMID 35661695, 2022). "Collectively, these data demonstrate the anti-fibrotic role of TP53TG1 in pulmonary fibrosis through inhibiting MYH9 protein expression, which might be attributed to decreased myofibroblasts differentiation and ECM deposition." (PMID 35661695, 2022). "Among them, we focused on the up-regulated protein MYH9 in pulmonary fibrosis." (PMID 35661695, 2022). "Further studies about the functions of MYH9 on lung fibroblast-to-myofibroblast differentiation may provide insights into the discovery of new treatment for pulmonary fibrosis." (PMID 33519439, 2020). "TP53TG1 as a MYH9 inhibitor might be target for the control of pulmonary fibrosis." (PMID 35661695, 2022). "Although TGF-β1-treated MRC-5 cell is a classic model of studying fibroblast differentiation, it is not identical with fibroblasts from idiopathic pulmonary fibrosis patients, and much work about MYH9-regulated fibroblast differentiation remains to be investigated." (PMID 33519439, 2020).
sensorineural deafness (3 papers, 2014 to 2024). "We over-expressed four mutant forms of Drosophila myoII in Johnston’s organ that contain variants commonly found in individuals with MYH9-related disorders who have sensorineural hearing loss and observed scolopidial detachment with variable penetrance in all variant forms of myoII." (PMID 27331610, 2016).
systemic lupus erythematosus (3 papers, 2014 to 2025). An autoimmune multi-organ disease typically associated with vasculopathy and autoantibody production. "Lastly, we analysed clinical and laboratorial baseline data according to MYH9 E1 haplotype, in order to evaluate if genotype was related to lupus activity." (PMID 24658608, 2014).
anemia (2 papers, 2015 to 2022). A reduction in the number of red blood cells, the amount of hemoglobin, and/or the volume of packed red blood cells. "As expected, knocking out of Myh9 also caused anemia and pancytopenia in Myh9fl/fl:Mx1-Cre mice, finally leading to an early lethality." (PMID 35740994, 2022).
atherosclerosis (2 papers, 2024 to 2025). A disease characterized by the build-up of fatty material and calcium deposition in the arterial wall resulting in partial or complete occlusion of the arterial lumen. "lncRNA TPRG1-AS1 promotes the degradation of MYH9 in HASMC cells through the ubiquitin-proteasome pathway, inhibits the migration of HASMCs, and alleviates atherosclerosis in mice." (PMID 39408647, 2024).
autosomal dominant macrothrombocytopenia (2 papers, 2012 to 2017). This syndrome is characterized by congenital thrombocytopenia associated with the presence of large platelets. "Mutations in the gene encoding NMMHC-IIa (MYH9) in cases with MYH9-related disorders cause autosomal dominant macrothrombocytopenia and bleeding associated with other complex pathobiologies." (PMID 28134622, 2017).
autosomal dominant non-syndromic hearing loss (2 papers, 2024 to 2026). "Currently, variants of MYH9 and MYH14 genes are associated with autosomal dominant nonsyndromic hearing loss, DFNA17 and DFNA4A, respectively." (PMID 38562617, 2024). "MYH9 and MYH14 are identified as chromosomal loci of autosomal dominant nonsyndromic hearing loss, DFNA17 and DFNA4A, respectively." (PMID 38562617, 2024). "In addition, the MYH9 gene is also known to be causative of autosomal dominant non-syndromic hearing loss (DFNA17)." (PMID 41751538, 2026).
cerebrovascular disease (2 papers, 2017 to 2018). "Both cerebrovascular disease and DKD were the main vascular complications of T2DM, which implies similar molecular mechanisms in the association of MYH9 rs3752462 with cerebrovascular disease and DKD." (PMID 29862302, 2018).
clear cell renal cell carcinoma (2 papers, 2024). "We further examined the expression of MYH9 in clear cell renal cell carcinoma (ccRCC) tissues and adjacent normal renal tissues, along with the activation of PI3K and AKT." (PMID 39440063, 2024). "In the context of clear cell renal cell carcinoma (ccRCC), Several studies have examined MYH9's role in tumor metastasis." (PMID 39440063, 2024).
cleft lip (2 papers, 2015 to 2026). Congenital defect in the upper lip where the maxillary prominence fails to merge with the merged medial nasal prominences. "This is particularly notable in light of the fact that several studies have shown human cleft lip associated with mutations in MYH9, which encodes NMHCIIA." (PMID 41231213, 2026). "The involvement of NMHCIIA in palate development takes on particular significance in light of multiple reports that the MYH9 gene locus is associated with non-syndromic cleft lip and palate in humans." (PMID 25848986, 2015). "Previous studies indicate that CDH1, CTNND1, and MYH9 gene disruption may contribute to cleft lip in humans." (PMID 41231213, 2026). "Single-nucleotide variants in MYH9, encoding non-muscle myosin IIA, are associated with non-syndromic cleft lip with or without cleft palate in humans." (PMID 41231213, 2026).
colorectal adenocarcinoma (2 papers, 2019 to 2022). The most common type of colorectal carcinoma. "The positive rates of MYH9 protein in colorectal adenocarcinoma tissues and para-cancerous tissues were 51.6% and 11.5%, respectively." (PMID 35646686, 2022).
dilated cardiomyopathy (2 papers, 2019 to 2024). Cardiomyopathy which is characterized by dilation and contractile dysfunction of the left and right ventricles. "These proteins are closely related to dilated cardiomyopathy (LMNA and MYH9), fibrosis (Vim), monocarboxylate transport (Slc16a1), vascular function (Cbx3 and Hnrnpn1), and endocytic trafficking (Snx5)." (PMID 39502510, 2024).
epilepsy (2 papers, 2024). A brain disorder characterized by episodes of abnormally increased neuronal discharge resulting in transient episodes of sensory or motor neurological dysfunction, or psychic dysfunction. "In summary, the endothelial-specific knockout of Myh9 results in the disruption of BBB integrity, which in turn exacerbates damage caused by BBB-associated diseases, such as epilepsy." (PMID 39404399, 2024). "Some genes have been identified as modifiers of SCN1A-related seizure before, but all of these were epilepsy-related genes; no MYH9-modified seizure has been reported before." (PMID 39202364, 2024).
gray platelet syndrome (2 papers, 2014 to 2018). Gray platelet syndrome (GPS) is a rare inherited bleeding disorder characterized by macrothrombocytopenia, myelofibrosis, splenomegaly and typical gray appearance of platelets on Wright stained peripheral blood smear. "Changes in the MT content of platelet marginal band was also reported in other giant platelet disorders such as MYH9-related disorders or Gray platelet syndrome." (PMID 30336771, 2018).